MAGOH (mago homolog, exon junction complex subunit)
Diseases named in the same sentence as MAGOH in open-access papers (continued):
Sharing a sentence is not in itself a finding about the gene and the disease.
PRLomas (1 paper, 2019). "However, PLS-DA analysis neatly revealed a different expression pattern between PRLomas and NPs, and VIP score analysis identified three components with high capacity to discriminate between both populations (RAVER1, MAGOH, and RNU11)." (PMID 31561558, 2019).
tumor (10 papers, 2015 to 2024). "The present study therefore comprehensively inspected the associations of MAGOH expression with the clinical features, prognosis, biological activities, tumor immunity, gene variations, and treatment responses in patients with LGG." (PMID 37390121, 2023). "Because the novel immunotherapy agent ICB has shown curative activity in the treatment of variant tumor types, the connection between MAGOH expression and ICPGs expression was evaluated in LGG patients." (PMID 37390121, 2023). "The results showed that MAGOH knockdown notably decreased the expression of MAGOH in tumor tissues and inhibited tumor growth in the two GC cell lines." (PMID 38268030, 2024). "The results showed that the expression of MAGOH was significantly higher in tumor tissues than in neighboring normal tissues." (PMID 38268030, 2024). "Taken together, our data suggested that MAGOH facilitated the proliferation, migration, and invasion of GC cells in vitro and thereby exerted a tumor-promoting effect." (PMID 38268030, 2024). "MAGOH expression was positively associated with ESTIMATE, stromal and immune scores, but inversely associated with tumor purity in the TCGA and CGGA datasets." (PMID 37390121, 2023). "The levels of MAGOH protein were discovered to be higher in LGG tissues than in tumor-adjacent tissues, with the results quantified by ImageJ software." (PMID 37390121, 2023). "In fact, tumor samples showing chiasmatic compression were all men with low MAGOH expression levels (with the exception of one woman)." (PMID 31561558, 2019). "MAGOH was strongly differentially expressed between tumor ER+ and TN subtypes, while MAGOHB was regulated by estrogen in MCF7 cells." (PMID 28263985, 2017). "In addition, high MAGOH expression was significantly correlated with advanced tumor stage and abundant tumor lymphatic metastasis, supporting the observation that high MAGOH expression is associated with low survival in GC patients." (PMID 38268030, 2024). "Because the expression of MAGOH was positively correlated with advanced tumor stage and abundant tumor lymphatic metastasis in GC patients, we wanted to determine whether MAGOH accelerated the migration and invasion of GC cells." (PMID 38268030, 2024). "In addition, IHC staining revealed decreases in the expression of the cell proliferation marker Ki67 and the antiapoptotic protein Bcl-2 in MAGOH-knockdown tumors, indicating that MAGOH knockdown inhibited tumor growth." (PMID 38268030, 2024). "This pathway can be activated in GC by overexpression of HRC (Histidine-rich calcium binding protein), upregulation of MAGOH and MAGOHB, and overexpression of YAP1 (Yes-associated protein 1), and subsequently promotes the tumour cell proliferation, migration, and invasion." (PMID 37037864, 2023). "Next, we investigated MAGOH and MAGOHB expression (here, considered MAGOH plus MAGOHB expression) in 5,715 tumour samples from 14 cancer types." (PMID 37294214, 2023). "MAGOH and MAGOHB are aberrantly expressed in different tumour types while their knockdown affected the development of gastric cancer." (PMID 37294214, 2023). "Our analyses showed that MAGOH/MAGOHB display increased expression in the 14 cancer types analysed in relation to normal counterparts, suggesting a broad involvement in tumour development." (PMID 37294214, 2023). "In the present study, we determined that MAGOH and MAGOHB are highly expressed in multiple tumour types." (PMID 37294214, 2023). "Six genes overlapped in the three top 50 lists for tumor response, overall clinical response, and PFS, including MAGOH, C16orf87, ORC1, NAA35, PWP2, and SIAH2." (PMID 35892846, 2022). "Also using our expression data, we identified several RNA processing factors that were differentially expressed between tumor subtypes and/or regulated by estrogen receptor, including YBX1, YBX2, MAGOH, MAGOHB, and PCBP2." (PMID 28263985, 2017).
tumor (continued). "Thus, we propose that in GBM cells, high MAGOH/MAGOHB expression would prevent aberrant splicing events that could ultimately compromise cell cycle and division, critical steps for tumour growth." (PMID 37294214, 2023). "Similar results have previously been described for other types of cancer where both MAGOH and MAGOHB had to be depleted to gain a sufficient KD of MAGOH/MAGOHB protein levels to interrupt EJC function and to reduce tumor cell viability as well as Xenograft tumor growth in mice." (PMID 36497117, 2022).
cancer (8 papers, 2021 to 2025). A tumor composed of atypical neoplastic, often pleomorphic cells that invade other tissues. "Misexpression of MAGOH is correlated with the progression of certain cancers as it is required to safeguard the splicing of cell division and cell cycle genes; thus, MAGOH is now considered an oncogene." (PMID 40251862, 2025). "Exon junction complex (EJC) core components, such as MAGOH (mago-nashi homolog), play important roles in the progression of human cancers regulated by alternative splicing." (PMID 38268030, 2024). "Pan-cancer analysis of MAGOH expression verified that higher MAGOH expression was interrelated with shorter OS, higher expression of ICPGs, and a greater TMB burden in pan-LGG." (PMID 37390121, 2023). "Analysis of pan-cancer gene expression data indicated that MAGOH was prodigiously expressed in several types of cancer." (PMID 37390121, 2023). "GSVA analysis also found that high-MAGOH expression correlated with immune responses and cancer-connected signaling pathways." (PMID 37390121, 2023). "The EJC, and especially MAGOH, has been shown to be involved in the development and progression of several cancers." (PMID 36497117, 2022). "In recent years, the role of MAGOH in tumorigenesis has been elucidated for numerous cancers." (PMID 38268030, 2024). "We next investigated whether high expression of MAGOH/MAGOHB is necessary to maintain cancer-relevant phenotypes." (PMID 37294214, 2023). "A role of MAGOH for tumorigenesis has been described in some cancers." (PMID 36497117, 2022). "We investigated MAGOH and MAGOHB expression using datasets from GTex (Genotype-Tissue Expression and TCGA (The Cancer Genome Atlas)." (PMID 37294214, 2023). "MAGOH/MAGOHB were overexpressed (p-value <0.01, Wilcoxon rank sum test) in all analysed cancers compared to their normal counterparts." (PMID 37294214, 2023). "MAGOH and MAGOHB as reciprocal paralog dependencies across cancer types suggest a rationale for targeting the MAGOHB-IPO13 axis in cancers." (PMID 35057823, 2022). "High expression of MAGOH and MAGOHB affect cancer-relevant phenotypes." (PMID 37294214, 2023). "Until now, the functional influence of MAGOH and MAGOHB in cancer has been essentially unexplored." (PMID 36497117, 2022). "Remarkably, we could recapitulate cancer-specific mRNA re-splicing in normal cells by knock-down of any of the core EJC proteins, EIF4A3, MAGOH, or RBM8A (Y14), implicating the EJC core as the repressor of mRNA re-splicing often observed in cancer cells." (PMID 34204574, 2021). "However, MAGOH and MAGOHB are still poorly understood in the context of cancer." (PMID 37294214, 2023). "Therefore, considering the impact of MAGOH and MAGOHB on cancer phenotypes and the dissimilar sensitivity to their knockdown between GBM and differentiated neuronal cells, targeting EJC members such as MAGOH and MAGOHB may be an alternative therapeutic strategy to treat GBM." (PMID 37294214, 2023).
MAGOH also shares sentences with these, for which no sentence is quoted: astrocytoma (1 paper); infection (1); oligodendroglioma (1); prostate carcinoma (1).